MDM2 (MDM2 proto-oncogene)
Diseases named in the same sentence as MDM2 in open-access papers (continued):
Sharing a sentence is not in itself a finding about the gene and the disease.
tumor (continued). "Targeting MDM2/TPSO (translocator protein), MDM2/PKC (protein kinase C), MDM2/NF-kB (nuclear factor-kappa B), MDM2/Bcl-2 (B-cell lymphoma-2) and MDM2/NFAT1 (nuclear factor of activated T-cells 1) had good anti-tumor activity and had the potential to reduce the adverse reactions of MDM2 inhibitors." (PMID 35831864, 2022). "FISH analysis revealed that the tumor was negative for MDM2/CDK4/FRS2 amplification." (PMID 36059611, 2022). "In our case, the tumor cells were diffusely positive for CDK4 but negative for MDM2." (PMID 34089125, 2022). "Lastly, the absence of MDM2, immunostaining does not necessarily signify that a tumor is not an OS." (PMID 35049602, 2021). "However, concerns rose with regards to the non-specific occurrence of MDM2 amplifications in a broad range of tumor types." (PMID 34312479, 2021). "Therefore, high levels of MDM2 and CD8+ T cells in the tumor microenvironment may be the reason why EC patients have a better OS." (PMID 34170849, 2021).
tumor (continued). "Importantly, MDM2 amplification in tumor cells has recently been suggested as a potential biomarker for HPD that is observed in some patients (5–29%) after ICI therapy, suggesting a potential role of MDM2 overexpression in cancer cell immune evasion." (PMID 32655895, 2020). "The role of MDM2 and NFAT1 in metabolism is not clearly understood but several studies have been demonstrated that MDM2 and NFAT1 play critical roles in metabolism regulation and may contribute to tumor progression." (PMID 32397368, 2020). "Moreover, inhibition of ERK signaling using a MAPK kinase inhibitor was demonstrated to exert a synergistic effect with RG7388 on tumor growth in DDLPS providing a rationale to investigate the potential of dual targeting of FGFR and MDM2 in WDLPS and DDLPS cells." (PMID 33092134, 2020). "In addition, enhanced MDM2 expression correlates with increased vascular endothelial growth factor (VEGF) expression which may facilitate vascularity, metastasis, and tumor growth." (PMID 32477121, 2020). "Unlike MDM2 inhibitors, USP7 inhibitors were well tolerated in mice at doses that effectively inhibited tumor growth, suggesting that pharmacological inhibition of USP7 may be safer than inhibition of MDM2." (PMID 32064756, 2020). "Interestingly, MDMX, or MDM2, knockdown does not correlate with a less aggressive tumor local-stroma invasion pattern, suggesting that MDM proteins facilitate intravasation and/or TNBC survival in the blood stream." (PMID 31489110, 2019). "So far, our preliminary studies have clearly suggested that MDM2 protein may be critically involved in the transcription control of vascular endothelial growth factor (VEGF) expression in several cancers and promote tumor angiogenesis." (PMID 30700046, 2019).
tumor (continued). "Downregulation of NudCD1 in tumor cells that showed a high expression of the protein resulted in a down-regulation of some oncogenic genes such as CTSL, MMP15, uPAR, VEGF, COX-2, S100A4, MUC1, MDM2 and RAC110 and an increase of the resistance to 5-fluorouracil-induced apoptosis." (PMID 29021621, 2017). "Therefore, we believe that MDM2-VEGF dual-targeting represents a novel cancer therapy strategy, not only against cancer cells, but also against the tumor microenvironment, especially tumor angiogenesis." (PMID 28274247, 2017). "This suggests that an in vivo assessment of MDM2 antagonists in combination with conventional AR antagonists or newer agents such as MDV3100 is required, which should result in highly effective tumour regression and may delay or prevent the onset of castrate resistant disease." (PMID 27729622, 2016). "Thus, it is imperative to completely understand how Mdm2 is regulated and how it regulates stemness as targeting Mdm2 to prevent CSCs may inadvertently promote CSC stemness and tumor heterogeneity." (PMID 27898034, 2016). "Furthermore, the MDM2 loci in this tumor was not included among the suspect chromothripsis regions for the tumor by Shatterproof and closer inspection of the region revealed that the amplification is likely the result of a simple tandem duplication." (PMID 26328271, 2015). "MDM2 amplification status by FISH could be of therapeutic importance, as amplified neoplasms, irrespective of precise histologic subtype, might be amenable in the future to targeted treatment with MDM2 antagonists." (PMID 25810689, 2015).
tumor (continued). "Because MDM2 amplification and the fusion transcripts PTGES3-PTPRB, HMGA2-DYRK2 and TMBIM4-MSRB3 were found both in the primary tumor and in the metastasis, they are components of the same clone and may be involved both in initiation and progression of the tumor." (PMID 25176350, 2014). "MDM2 amplification levels were not different regardless of histologic subtype or tumor recurrence." (PMID 25121597, 2014). "Our screens revealed that synergy between MDM2 inhibitors and PI3K pathway inhibitors, MEK inhibitors, BH3 mimetics, HDAC inhibitors, and dasatinib was far more prevalent than previously appreciated, occurring across multiple tumor cell types and genetic backgrounds." (PMID 24810962, 2014). "This conclusion may put forward that mdm2 in this lesion is not acting as oncogene, but rather act as a tumor suppressor gene or a smaller protein is expressed." (PMID 19445705, 2009). "Tumours with MDM2 amplification were grouped and compared to those with no MDM2 amplification." (PMID 18781178, 2008). "Interestingly, by this measure, the MDM2 SNP309 locus only significantly interacts with the age of tumor diagnosis in female carriers and not in male carriers." (PMID 18398474, 2008). "Additionally, if MRI reveals a fatty soft tissue tumor with heterogeneous signal intensity, septa < 2 mm, or a single non-fat nodule—regardless of the tumor’s maximum size—a biopsy with MDM2 determination is required to characterize the tumor before initiating treatment." (PMID 39997549, 2025).
tumor (continued). "Therefore, assuming that the ctDNA yield is proportional to tumor content, it may not be surprising that in our small series we could not detect MDM2 amplification in patients with tumors showing primarily well-differentiated histology." (PMID 34986184, 2022). "However, this may not necessarily mean that MDM2 cannot be used as a target for tumor growth inhibition." (PMID 34384473, 2021). "Likewise, mRNA levels of three oncogenes, namely ETS1, MDM2, and ARAF, were decreased by C treatment; on the contrary, the growth arrest and DNA-damage-inducible G (GADD45G), a stress-responsive gene involved in tumor suppression, was upregulated in C + AFB1 exposed cells." (PMID 33137966, 2020). "Moreover, not all samples from the same type of tumor, show Mdm2 overexpression." (PMID 32982771, 2020). "Therefore, MDM2 may be involved in TKIs resistance by promoting tumor angiogenesis although this mechanism has not been directly verified and requires further studies." (PMID 31440117, 2019). "Interestingly, such effects could be only achieved in stressed conditions such as serum deprivation or chemotherapeutic drug treatment, yet miR-17 reduced tumor growth by targeting murine double minute 2 (MDM2) under normal circumstances." (PMID 23391506, 2012).